TLR12P (toll like receptor 12, pseudogene)
Gene: Unitary pseudogene on chromosome 1 (33,466,249 to 33,468,954, forward strand). Ensembl gene ENSG00000234512.
Diseases named in the same sentence as TLR12P in open-access papers:
TLR12P is named in the same sentence as 2 diseases in open-access papers, as found by Europe PMC text mining. Sharing a sentence is not in itself a finding about the gene and the disease. The quoted sentences say what the papers report.
cancer (1 paper, 2022). A tumor composed of atypical neoplastic, often pleomorphic cells that invade other tissues. "Additionally, TLR9, TLR8-AS1, and TLR12P were infrequently detected in these cancer tissues." (PMID 35801728, 2022). "TLR1, TLR2, TLR3, TLR4, and TLR5 expression levels were high across the six immune subtypes in the pan-cancer data; TLR6, TLR7, TLR8, and TLR10 expression levels were moderate; and TLR9, TLR12P, and TLR8-AS1 expression levels were extremely low." (PMID 35801728, 2022).
TLR12P also shares sentences with these, for which no sentence is quoted: diabetes (2 papers).